KMT2C (lysine methyltransferase 2C)
Diseases named in the same sentence as KMT2C in open-access papers (continued):
Sharing a sentence is not in itself a finding about the gene and the disease.
tumor (continued). "Interestingly, Kmt2c KO tumours show higher mRNA and protein levels of the basal cytokeratin Krt6a, which is implicated in EMT." (PMID 36933062, 2023). "Combined with literature reports implicating KMT2C in chemotherapy response in hemopoeitic malignancies and solid tumors, our findings uncover a broader role for KMT2C in modulating therapeutic response in neoplasia." (PMID 36933062, 2023). "The most significantly increased protein was Lysine Methyltransferase 2C (KMT2C) is a potential tumor suppressor but has not been reported to be associated with CMV and is a novel finding." (PMID 37205661, 2023). "In contrast, low KMT2C expression correlates with bad prognosis in BCa and both truncation mutations as well as mutations in the plant homeodomain (PHD) of KMT2C have been shown to be tumour-promoting events." (PMID 35354467, 2022). "The research of Folkman’s innovative tumor angiogenesis hypothesis was published in 1971; since then, there has been great interest in understanding the role of the KMT2C gene." (PMID 35409657, 2022). "Here, we demonstrate that tumor cell ablation of mixed-lineage leukemia 3 and 4 (MLL3 and MLL4, also known as KMT2C and KMT2D, respectively), two enhancer-associated histone H3 lysine 4 (H3K4) mono-methyltransferases, increases tumor immunogenicity and promotes anti-tumor T cell response." (PMID 36323669, 2022). "We also demonstrated, for the first time, that the KMT2C gene may play a role of tumor suppressor in HNSCC, which opens new possibilities in the search for new targeted treatment approaches." (PMID 35664801, 2022). "Furthermore, KMT2 family genes, such as KMT2A, KMT2C, and KMT2D, were frequently mutated in TMB‐H or PD‐L1+ tumor samples." (PMID 33655698, 2021). "Next, we investigated whether down-regulation of CREBBP, KMT2C or NCOA2 could promote tumor progression in cuSCCs." (PMID 34398873, 2021). "These include the lysine methyltransferase genes KMT2C and KMT2D, which have been implicated in several other tumor types and suggests that chromatin remodeling activity may play a role in a subset of NECC." (PMID 32544169, 2020). "Collectively, these data indicate that both mutational inactivation and transcriptional downregulation via promoter methylation of KMT2C might contribute to reduced activity facilitating tumor development in several epithelial cancers." (PMID 30665945, 2019). "However, it is unknown whether loss of KMT2C and KMT2D induces similar or unique epigenetic alterations and which underlying pathways might drive metastasis in KMT2C- or KMT2D-deficient tumours." (PMID 38926506, 2024). "The most frequently mutated factors include the H3K4 mono-methyltransferases MLL3 and MLL4 (encoded by the genes KMT2C and KMT2D, respectively) and their cofactor, the H3K27 demethylase UTX (KDM6A); the prevalence of mutations affecting these factors indicates their broad roles as tumor suppressors." (PMID 37252797, 2023).
tumor (continued). "Interestingly, TTN, PIK3CA, MUC4, KMT2C, and MUC16 were the top mutations in both cohorts, which were reported to regulate various tumor biological processes in CC, indicating that they are less participated in the process of immune infiltration but mainly involved in tumorigenesis and progression." (PMID 33553190, 2021). "This may imply that KMT2C and KMT2D proteins exert coordinated and synergistic functions in enhancer elements and their loss during carcinogenesis deregulates cell adhesion and signaling with profound effects to tumor progression and invasion." (PMID 30665945, 2019). "KMT2C is known to modify mono-methylation of histone H3 lysine 4 (H3K4) at enhancers and plays a role as a haploinsufficient tumor suppressor." (PMID 40394211, 2025). "Therefore, KMT2C may serve as a promising target for tumor immunotherapy for certain diseases." (PMID 39165358, 2024). "A relatively high level of acquired alterations in RB1 (33%), the histone-lysine methyltransferase KMT2C (29%), and PTEN (19%) were also identified in the PD tumor samples, suggesting a role in driving resistance to therapy in this patient cohort." (PMID 37475004, 2023). "However, it is currently unclear whether KMT2C works as a tumor suppressor or as an oncogene." (PMID 37415738, 2023). "Collectively, these data imply that under the effect of TAOK3's phosphorylation, KMT2C mediates histone methylation and transcriptionally upregulates the expression of IRGM together with ETV5, and tumor autophagy is augmented consequently." (PMID 37705061, 2023). "The N-terminal PHD region of MLL3/KMT2C has been shown to bind the BAP1-containing PR-DUB complex, which is also a tumor suppressor and acts as a deubiquitinase for histone H2A." (PMID 37370727, 2023). "High levels of KMT2A, KMT2C, KMT2E, and KMT2H were shown to be strongly connected with types 3 and 5 infiltrations (C3 and C5), indicating that greater gene expression is linked to a healthy immune system and that these genes may play an important function in tumor suppression." (PMID 35058979, 2022). "These genes were KMT2C, MST1, HLA-A and BCL11A which are involved in epigenetic modifications, tumor suppression and immune surveillance." (PMID 35504960, 2022). "UroAmplitude identified TERT, PLEKHS1, FOXQ1, KMT2C, and ERBB2 somatic events in urine collected prior to resection of an HG T1 multifocal tumor." (PMID 36233691, 2022). "KMT2C, a member of the KMT2 family, has been identified as a tumour suppressor that is frequently altered in multiple cancers." (PMID 36333792, 2022). "Only six genes were present in both tumor initiation and tumor evolution stage: MUC4, MUC16, USP6, BCLAF1, KMT2C, and NOTCH2." (PMID 34918496, 2022). "Epigenetic alterations relating to histone methylation (KMT2D, KMT2C, EZH2), histone acetylation (CREBBP, EP300), and DNA methylation (TET2) play an important role in tumor progression for FL and DLBCL." (PMID 36497332, 2022). "We concluded that patients with high expression levels of XIST tended to show high expression levels of KMT2C and low expression levels of SOIST2, OCT4 and Nanog as well as high 5-year tumor-free survival rate." (PMID 32943985, 2020). "Out of 16 analyzed TNBC tumors, six, three, two, and one tumor harbored SVs involving RB1, KMT2C, PTEN, or RUNX1, respectively." (PMID 28636652, 2017). "Our previous study, together with others, demonstrated that KMT2C and KMT2D function as tumor suppressors." (PMID 28055972, 2017).
tumor (continued). "In addition, we identified mutations in epigenetic regulation genes, such as KMT2D, KMT2E, SMYD3, ASH1L, KMT2C, and KMD4B, in the tumor clones." (PMID 38010945, 2024). "In addition, mutations on diverse epigenetic regulators such as MLL3 (KMT2C), KDM6A, CREBBP (CBP), ARID1A and ARID1B have been observed in some HCL patients, which may promote the disease progression by turning on oncogenic pathways and off tumor suppressive pathways via epigenetic modifications." (PMID 37543582, 2023). "Likewise, KMT2C, CREBBP, and NCOA2 were identified to demonstrate tumor-suppressive roles in the initiation and progression of human cSCC." (PMID 36980718, 2023). "Kmt2c knock out mice develop tumours earlier, irrespective of the oncogene, assigning a bona fide tumour suppressor role for KMT2C in mammary tumorigenesis." (PMID 36933062, 2023). "Specifically, we show that mammary glands lacking KMT2C activity develop tumours with shorter latency than their wild-type (WT) counterparts." (PMID 36933062, 2023). "Interestingly, SPHK1, with known oncogenic characteristics was the only gene upregulated with > 2.0-fold change and tumour suppressors namely AKR1B1 and KMT2C were down regulated in PDAC-CP." (PMID 35854233, 2022). "We found that knockdown of KMT2C, a key molecule in the COMPASS complex, in human cuSCC cell lines accelerated in vitro proliferation and in vivo xenograft growth, supporting a role for this gene as a tumor suppressor in advanced disease." (PMID 34398873, 2021). "Altogether, these data indicate that KMT2C controls the epigenetic status of genes involved in DDR and DNA repair and directly or indirectly their expression levels, even in tissues in which a tumor suppressor role of KMT2C has yet to be established." (PMID 30665945, 2019). "We then verified the expression level of KMT2C, ASXL1, and MCM8 in CCA using the GEPIA database and found that all of the three genes, especially ASXL1 (p < 0.05) and MCM8 (p < 0.05), were overexpressed in tumor tissues." (PMID 32010606, 2019). "Similarly, Kmt2c suppression also attenuated MYC-induced apoptosis, as shown by tumor histology and apoptosis by TUNEL assay, 5 days after hydrodynamic delivery of transposon vectors encoding Myc together with GFP-linked shRNAs targeting Kmt2c (or Renilla luciferase as a control)." (PMID 37261974, 2023). "KMT2C and KMT2H expressions were not substantially associated with RNAss, despite other members of the KMT2s family being strongly negatively correlated with tumor stem-like features assessed by mRNA (RNAss)." (PMID 35058979, 2022). "KMT2C and KMT2D proteins restrain cell proliferation and could be considered tumor suppressors." (PMID 34572812, 2021). "Additionally, in 213 ccRCC, 113 pRCC, and 65 chRCC, of the most commonly mutated HMTs, SETD2, and KMT2C were most frequently mutated in ccRCC and pRCC subtypes, whereas SETD2 was mutated in less than 1.54% of tumor samples and KMT2C did not exhibit mutation in chRCC." (PMID 30755832, 2019). "Unlike KMT2A and KMT2B, KMT2C and KMT2D are known to impede cell proliferation and, oftentimes, are considered as tumor suppressors." (PMID 33302406, 2020). "The close family members of KMT2A, KMT2C, and KMT2D also have negative effects on tumor cell growth, supporting the tumor-suppressive role of the KMT2 family." (PMID 28968975, 2017).
neurodevelopmental disorder (14 papers, 2017 to 2026). A behavioral and cognitive disorder with onset during the developmental period that involves impaired or aberrant development of intellectual, motor, or social functions. "By exploring this phenotype in human subjects with KMT2C mutations, we may gain valuable insights into the role of KMT2C in social behavior and its potential implications for neurodevelopmental disorders." (PMID 37538398, 2023). "In summary, our study contributes to the understanding of KMT2C-related neurodevelopmental disorders." (PMID 37538398, 2023). "Through the large scale application of diagnostic whole exome sequencing for unexplained neurodevelopmental disorders in the clinical genetics centers at the Radboudumc and Maastricht UMC, we identified five de novo KMT2C mutations." (PMID 29069077, 2017).
hematological malignancies (4 papers, 2016 to 2024). "Studies of KMT2C have found that it is aberrantly expressed in many diseases, mainly tumors and hematological disorders." (PMID 39165358, 2024). "The KMT2C/MLL3 frameshift mutation (p.Y816fs) in patient 791 had never been identified in hematological malignancies before." (PMID 27602765, 2016).
adenocarcinoma (2 papers, 2017 to 2024). A common cancer characterized by the presence of malignant glandular cells. "Alterations affecting SWI/SNF-encoding genes ARID1A, SMARCA4 and PBRM1 were more common in adenocarcinomas, whereas ESCCs contained more frequent alterations in histone-modifying factors KDM6A (UTX), KMT2D (MLL2) and KMT2C (MLL3)." (PMID 28052061, 2017).
prostate (2 papers, 2022 to 2025). "Taken together, we identify the SET domain deletion of KMT2C as a novel driver of prostate carcinogenesis in murine models and suggest that the presence of mutated forms is a biomarker for poor outcome in PCa patients." (PMID 35354467, 2022). "High-throughput sequencing methods such as single-cell RNA-seq have enabled deep characterization of the prostate BCC genome, revealing key driver mutations of CASC5, NUTM1, PTPRC, KMT2C, and TBX3, genes also involved in chromatin remodeling and stem cell regulation." (PMID 40124187, 2025).
brain disorder (1 paper, 2025). A disease affecting the brain or part of the brain. "To determine the biological roles of KMT2C and its mechanistic link to brain disorders, we did a PPI network analysis using the STRING database." (PMID 41301465, 2025).
epithelial neoplasm (1 paper, 2021). A benign or malignant neoplasm that arises from and is composed of epithelial cells. "Also referred to as MLL3, KMT2C is a component of the activating signal cointegrator complex, with overexpression documented in a number of epithelial neoplasms." (PMID 34445161, 2021).
neurological disorders (1 paper, 2024). "Differentially expressed or spliced genes in the compound heterozygous mutant animals include ortholougus genes causing human neurological disorders such as Abca7, Zfp365, Kmt2c, Madd and Tcf4." (PMID 37294900, 2024).
KMT2C also shares sentences with these, for which no sentence is quoted: Kabuki syndrome (7 papers); papillary thyroid cancer (4); Kabuki syndrome 1 (3); larynx cancer (3); myeloid malignancies (3); non-small cell lung carcinoma (3); psychiatric disorder (3); B cell lymphoma (2); clear cell carcinoma (2); congenital heart defects (2); depression (2); diabetes mellitus (2); immune diseases (2); infection (2); kidney cancer (2); membranous nephropathy (2); microcephaly (2); multiple myeloma (2); neuroblastoma (2); non-Hodgkin lymphoma (2); osteoporosis (2); peripheral T-cell lymphoma (2); sarcoma (2); Wiedemann-Steiner syndrome (2); acinar cell carcinoma (1); Acute hepatitis (1); acute leukemia (1); anal carcinoma (1); anemia (1); Anxiety (1).
A further 89 diseases each share a sentence with KMT2C in 1 paper.